PCSK9 (proprotein convertase subtilisin/kexin type 9)
Diseases named in the same sentence as PCSK9 in open-access papers (continued):
Sharing a sentence is not in itself a finding about the gene and the disease.
cardiovascular disease (continued). "Proprotein convertase subtilisin/kexin type 9 (PCSK9) is a pivotal regulator of lipid metabolism and a validated therapeutic target in cardiovascular disease (CVD)." (PMID 41918565, 2026). "In this study, we created a library of siRNA conjugates with the GalNAc L-96 ligand to suppress the expression of the PCSK9 gene associated with elevated LDL and an increased risk of developing cardiovascular diseases." (PMID 41683454, 2026). "The discovery of proprotein convertase subtilisin/kexin type 9 (PCSK9) in 2003 marked a significant milestone in the understanding of cholesterol metabolism and cardiovascular disease." (PMID 40764605, 2025). "Loss-of-function mutations in PCSK9 are associated with decreased LDL-C levels and a reduced risk of cardiovascular disease." (PMID 39969435, 2025). "Proprotein convertase subtilisin/kexin type 9 (PCSK9)inhibitors have shown promise in cardiovascular disease management in the general population, but research on their use in kidney transplant patients is limited to case reports and small-scale studies." (PMID 41478627, 2025). "Gain-of-function mutations in PCSK9 produce increased levels of LDL cholesterol and an increased risk of cardiovascular disease." (PMID 40870420, 2025). "In recent years, research on PCSK9 inhibitors for the prevention of cardiovascular disease in the general population has been widely conducted, showing good efficacy and safety." (PMID 41478627, 2025). "The serine protease proprotein convertase subtilisin/kexin type 9 (PCSK9), a protein closely related to cholesterol regulation, plays an important role in various diseases, including cardiovascular diseases." (PMID 40214585, 2025). "As a proof of concept, PCSK9 was selected for its relevance to cardiovascular disease and suitable sequence structure." (PMID 40933564, 2025). "PCSK9 inhibitors represent a breakthrough in the management of cardiovascular disease, offering a potent therapeutic option for lowering LDL cholesterol (LDL-C) and reducing cardiovascular risk, particularly in patients who are unable to tolerate statins." (PMID 40110272, 2025). "For instance, lipid-based nanoparticles delivering CRISPR/Cas9 targeting Pcsk9 achieved over 80 % editing efficiency in liver cells, which is relevant since Pcsk9 influences inflammatory responses and cardiovascular disease." (PMID 40687553, 2025). "In both people and rats, blood levels of PCSK9 exhibited a favorable correlation with aging and the incidence of cardiovascular disease." (PMID 40354375, 2025). "PCSK9 inhibitors represent a revolutionary class of lipid-lowering therapeutics that have transformed cardiovascular disease management." (PMID 40764605, 2025). "Statins have shown to have some additional inhibitory effects on platelet aggregation and activation beyond lipid-independent mechanisms, potentially protecting against cardiovascular disease despite elevated levels of PCSK9." (PMID 40480650, 2025). "Recent research has brought to light the pivotal role of PCSK9 in various aging-related cardiovascular diseases." (PMID 40354375, 2025). "Collectively, these studies expand the understanding of the pleiotropic effects of PCSK9, demonstrating its clinical potential across cardiovascular diseases, organ transplantation, and renal protection." (PMID 41478627, 2025). "Furthermore, a decrease in platelet reactivity has been shown with PCSK9 inhibition treatment, suggesting that PCSK9 inhibitors as well as aspirin may reduce the risk of cardiovascular disease by counteracting the enhancing effects of PCSK9 on platelet reactivity." (PMID 40480650, 2025).
cardiovascular disease (continued). "Lowering low-density lipoprotein cholesterol (LDL-C) through PCSK9 inhibition represents a new therapeutic approach to preventing and treating cardiovascular disease (CVD)." (PMID 38198221, 2024). "In this research, we found that articles on cardiovascular diseases and PCSK9 were published in 590 journals." (PMID 38887452, 2024). "Three major trials— FOURIER, SPIRE‐1 and SPIRE‐2, and the ODYSSEY Outcomes trial—have provided significant evidence for the use of PCSK9 inhibitors in managing cardiovascular diseases." (PMID 39479289, 2024). "PCSK9 has been widely studied and applied in the detection screening, prevention, and treatment of cardiovascular diseases." (PMID 38887452, 2024). "Since PCSK9 plays a key role in the development of cardiovascular disease (CVD), exploration of PCSK inhibitors from natural products are beneficial for drug discovery of CVD treatment." (PMID 39404968, 2024). "The review article summarizes recent findings on the biological mechanisms of PCSK9 and its role in cardiovascular disease, focusing on how PCSK9 inhibition can reduce cardiovascular risk." (PMID 39539858, 2024). "These trials have also shown that PCSK9 inhibitors are effective and safe for the treatment of several cardiovascular disorders." (PMID 39770423, 2024). "Addressing these gaps will provide a more comprehensive assessment of PCSK9 inhibitors' clinical value and guide their optimal use in managing cardiovascular diseases." (PMID 39650150, 2024). "Cholestyramine is recommended in combination with statins and ezetimibe for patients with ASCVD or those at high risk for cardiovascular disease who have LDL-C levels above target and are unable to use PCSK9 inhibitors [+, IIb, C]." (PMID 39697215, 2024). "The primary objective of this study was to conduct a cost–utility analysis of proprotein convertase subtilisin/kexin type 9 (PCSK9) inhibitors in real-world, comparing their use with standard care for managing cardiovascular disease." (PMID 39452487, 2024). "PCSK9 plays a pivotal role in cholesterol metabolism by promoting the degradation of LDL receptors, thereby influencing cardiovascular disease risk." (PMID 39254080, 2024). "Previous 2x2 factorial MR studies have identified combination therapies primarily within cardiovascular disease between PCSK9 and CETP inhibition, NPC1L1 and HMGCR inhibition, and IL-6 and PCSK9/CETP/NPC1L1 inhibition." (PMID 38962682, 2024). "Lipid-lowering therapy with the PCSK9 inhibitor evolocumab improved clinical efficacy, reducing total primary end-point events in patients with stable cardiovascular disease receiving statin therapy." (PMID 39539858, 2024). "The siRNA-mediated degradation of PCSK9 mRNA effectively blocks the synthesis of PCSK9 protein, offering a new therapeutic approach for treating cardiovascular diseases." (PMID 39040999, 2024). "For example, statins and proprotein convertase subtilisin/kexin type 9 (PCSK9) inhibitors are used to reduce low-density lipoprotein cholesterol (LDL-c) to prevent cardiovascular disease." (PMID 39167758, 2024). "This article reviews the current understanding of the mechanisms of PCSK9 action in the cardiovascular system and its contribution to cardiovascular diseases." (PMID 38886277, 2024). "Through our analysis, we found a total of 3,243 institutions involved in the research on cardiovascular diseases and PCSK9." (PMID 38887452, 2024). "PCSK9 has garnered significant attention as a promising therapeutic target, revolutionizing the landscape of lipid management and cardiovascular disease prevention." (PMID 38105401, 2024).
cardiovascular disease (continued). "New agents targeting PCSK9 have significantly improved the symptoms and prognosis of patients with major cardiovascular diseases." (PMID 39736777, 2024). "Numerous large-scale randomized clinical trials have consistently shown a decrease in MACEs rates with the use of PCSK9 inhibitors in individuals with established cardiovascular disease." (PMID 39259104, 2024). "Another benefit of PCSK9 inhibition is reductions in lipoprotein(a) levels, a LDL-like lipoprotein associated with cardiovascular diseases." (PMID 36855099, 2023). "Several clues suggest that PCSK9 represents a pivotal factor in cardiovascular disease, in part independent from its effects on lipid metabolism." (PMID 37109259, 2023). "Previous studies have shown that individuals with mutations that enhance PCSK9 levels have elevated LDL cholesterol, and are at increased risk of developing cardiovascular disease, including heart attacks and strokes." (PMID 37222281, 2023). "Previous 2×2 factorial MR studies have identified combination therapies primarily within cardiovascular disease for PCSK9 and CETP inhibition, NPC1L1 and HMGCR inhibition, and IL-6 and PCSK9/CETP/NPC1L1 inhibition." (PMID 37398493, 2023). "Conversely, individuals with mutations that result in low levels of PCSK9 have lower LDL and lower risk of cardiovascular disease." (PMID 37222281, 2023). "Cardiovascular diseases: DENV-infected patients are found to have higher levels of proprotein convertase subtilisin/Kexin type 9 (PCSK9) in their plasma." (PMID 37242305, 2023). "The function of PCSK9 was not only to regulate cholesterol and prevent cardiovascular diseases, but also to potentiate the application of PCSK9 inhibitors in ischemia-reperfusion injury and enhance the synergistic anticancer effect of PD-1." (PMID 37860186, 2023). "Recently, PCSK9 inhibitors were shown to have added benefit in the treatment of cardiovascular diseases." (PMID 38094682, 2023). "PCSK9 inhibitors decrease LDL-C by 50–60% from the baseline, lower cardiovascular disease risk similar to statins, and demonstrate strong additive effect when administered in combination with statins." (PMID 37109734, 2023). "Extensive research has been conducted on the function of PCSK9 due to its involvement in cholesterol metabolism and cardiovascular diseases." (PMID 37860715, 2023). "•PCSK9 inhibition attenuates the progression of cardiovascular disease and NAFLD progression in aging animals." (PMID 38094682, 2023). "In 2006, it was discovered that mutations in the PCSK9 gene led to higher LDL-C and cardiovascular disease (CVD) risk." (PMID 36895542, 2023). "Although existing drugs, such as statins and PCSK9, have proven their efficacy, cardiovascular diseases continue to be the cornerstone of morbidity and mortality in industrialized countries." (PMID 37627820, 2023). "AAV9’s liver tropism also facilitates CRISPR-based gene therapy for liver targets related to cardiovascular disease including atherosclerotic cardiovascular disease (PCSK9)." (PMID 37840136, 2023). "Elevated levels of PCSK9 have been linked to an increased LDL-c plasma levels, thereby increasing the risk of cardiovascular disease (CVD), making it an attractive target for therapeutic interventions." (PMID 37860715, 2023). "The levels of active and cleaved PCSK9 forms in HDL should be further investigated for their potential use as biomarkers for cardiovascular disease." (PMID 36067830, 2022). "Effective studies of cardiovascular diseases related to PCSK9 require the use of appropriate cells and animal models." (PMID 36005422, 2022). "This study applied CRISPR/Cas9 to PCSK9, providing a new idea for the prevention of cardiovascular diseases." (PMID 36230934, 2022).
cardiovascular disease (continued). "Drugs from the PCSK9 inhibitor group reduce the incidence of cardiovascular morbidity and mortality in patients with known cardiovascular disease." (PMID 35877573, 2022). "Low-density lipoprotein (LDL) is believed to be one of the risk factors for cardiovascular diseases, and contents of LDL and LDL-receptor are elaborately regulated by the protein convertase subtilisin/kexin type 9 (PCSK9) protein." (PMID 35414791, 2022). "According to the other study, evolocumab, the PCSK9 inhibitor, can lower LDL cholesterol by as much as 60% and reduce the risk of cardiovascular events among patients with established cardiovascular disease." (PMID 36082127, 2022). "Based on this process, studies have shown that the PCSK9-mediated increase in circulating LDL is closely related to the progression of cardiovascular diseases such as coronary heart disease." (PMID 36230934, 2022). "Proprotein convertase subtilisin/kexin type 9 (PCSK9) is a crucial factor in the development and progression of cardiovascular diseases." (PMID 36005422, 2022). "The therapeutic potential for genome editing in cardiovascular diseases and other diseases, of course, extends beyond PCSK9." (PMID 34981785, 2022). "While PCSK9 inhibitors have been introduced for the treatment of cardiovascular diseases, other potential effects of PCSK9 inhibitors, such as DR treatment, should be explored." (PMID 35600617, 2022). "Animal models of cardiovascular disease have been developed to conduct a comprehensive study of PCSK9′s pleiotropic involvement in cardiovascular disease progression, particularly in platelet activation." (PMID 36005422, 2022). "Extensive research using experimental and clinical approaches has been directed toward exploring the functions of PCSK9 in cardiovascular diseases." (PMID 35207479, 2022). "Serum proprotein convertase subtilisin/kexin type 9 (PCSK9) levels have been recently recognized as biomarkers of low-grade inflammation and cardiovascular disease." (PMID 34560758, 2022). "For instance, gain-of-function variants in PCSK9 have been demonstrated to increase low-density lipoprotein (LDL) levels and thus risk for cardiovascular disease." (PMID 36778668, 2022). "Some studies have used rats in their research when studying the roles of PCSK9 in cardiovascular disease progression." (PMID 36005422, 2022). "This makes PCSK9 a potential target to be developed for the prevention and treatment of cardiovascular diseases." (PMID 35207479, 2022). "In further studies, we will screen desirable PCSK9 small molecule inhibitors which can reduce plasma PCSK9 levels in vivo to reveal more PCSK9 functions in cardiovascular diseases beyond LDL-cholesterol plasma level regulation." (PMID 35832650, 2022). "The important role of PCSK9 in lipid homeostasis brings to the fore an attractive target for many diseases, such as FH, cardiovascular disease and especially cancer." (PMID 36552895, 2022). "In this review we evaluate recent findings on PCSK9 functions in cardiovascular diseases beyond LDL-cholesterol plasma levels regulation." (PMID 33834043, 2021). "The identification of PCSK9 as a target for lipid-lowering drugs occurred as a result of the recognition that loss-of-function mutations of PCSK9 resulted in reduced circulating concentrations of LDL-C and a lower risk of cardiovascular disease." (PMID 34940615, 2021). "Understanding the factors that modulate interindividual variability of PCSK9 plasma levels is important for the better understanding of individual responses to treatment as well as the identification of new targets for cardiovascular disease treatment." (PMID 34659352, 2021). "Low plasma levels of Proprotein Convertase Subtilisin/Kexin 9 (PCSK9) are associated with decreased low-density lipoprotein (LDL) cholesterol and a reduced risk of cardiovascular disease." (PMID 34731223, 2021).
cardiovascular disease (continued). "A real-world study of 143 patients with HeFH and very high-risk status for cardiovascular disease revealed that only 45% achieved an LDL-cholesterol level of <55 mg/dl on triple therapy including a high-intensity statin, an ezetimibe, and a PCSK9 inhibitor." (PMID 33716107, 2021). "The discovery that loss-of-function mutations in PCSK9 lead to lower plasma levels of LDL cholesterol and protection from cardiovascular disease led to the therapeutic development of PCSK9 inhibitors at an unprecedented pace." (PMID 34322524, 2021). "Two large scale trials were conducted in parallel, Studies of PCSK9 Inhibition and the Reduction of Vascular Events (SPIRE) −1 and −2’, and the trials randomized 27,438 cardiovascular disease or high risk patients." (PMID 34071276, 2021). "Obtained results suggest a predictive role of PCSK9 levels for the occurrence of cardiovascular diseases and support the possible clinical role of PCSK9 inhibitors." (PMID 32456228, 2020). "On the contrary, loss-of-function mutations in PCSK9 are associated with low LDL-C concentrations and significantly reduced lifetime risk of cardiovascular disease." (PMID 33304274, 2020). "In patients with cardiovascular disease, PCSK9 blood concentrations were related to the frequent presence of necrotic cores in coronary plaques regardless of statin use." (PMID 32942987, 2020). "Considering these significant LDLc and cardiovascular mortality reductions, the introduction of PCSK9 inhibitors on a large scale, for the primary and secondary prevention of cardiovascular diseases, seems rational." (PMID 32375792, 2020). "PCSK9 has been primarily studied because of its important role in cardiovascular disease pathophysiology via regulation of LDL-C metabolism." (PMID 31748600, 2019). "Proprotein convertase subtilisin/kexin type 9 (PCSK9) inhibitors reduce the risk of cardiovascular events and all-cause mortality in patients at high risk of cardiovascular disease (CVD)." (PMID 29861477, 2018). "We predict that after surgery, the sudden drop in estrogen will lead to gradual increases in LDL and PCSK9, with concomitant decreases in HSP27 and HSP27 Ab, making these women more susceptible to cardiovascular disease risk." (PMID 30766717, 2018). "An additional focus of the GLAR for the coming years will be to observe if PCSK9-inhibitors will allow stopping or even preventing a progress of cardiovascular disease either as single therapy or in combination with other therapies." (PMID 28233268, 2017). "This review examines the most recent evidence and future prospects for the use of PCSK9 inhibitors in the prevention of cardiovascular disease." (PMID 27095708, 2016). "One example is PCSK9, where a loss-of-function variant is associated with lower levels of LDL cholesterol and protection from cardiovascular disease." (PMID 23696745, 2013). "It is known that gaining the Pcsk9 function mutations is coupled with cardiovascular diseases and autosomal dominant hypercholesterolemia, while their loss lead to decreased LDL-C levels in plasma, consequently mitigating the risks of cardiovascular diseases." (PMID 40725196, 2025).